SIRT6 (sirtuin 6)
Diseases named in the same sentence as SIRT6 in open-access papers (continued):
Sharing a sentence is not in itself a finding about the gene and the disease.
experimental autoimmune encephalomyelitis (6 papers, 2020 to 2023). An autoimmune demyelinating disease of the central nervous system that is produced experimentally in animals by the injection of homogenized brain or spinal cord in Freund's adjuvant. "Also, the use of the same SIRT6 inhibitor impaired dendritic cell migration, downregulated pathogenic T cell inflammatory responses, and delayed the onset of experimental autoimmune encephalomyelitis, the most common animal model of multiple sclerosis." (PMID 36109503, 2022). "In the same line, recent findings in an experimental autoimmune encephalomyelitis (EAE) model show that acute pharmacological SIRT6 inhibition decreases TNFα secretion." (PMID 35150745, 2022). "Recently, inhibition of the NAD+-dependent deac(et)ylase sirtuin 6 was demonstrated to delay the onset of experimental autoimmune encephalomyelitis, by dampening DC trafficking towards inflamed LNs." (PMID 35457169, 2022). "Based on these studies, here we used the same small molecule SIRT6 inhibitor to explore the role of SIRT6 in the development of experimental autoimmune encephalomyelitis (EAE), a prototypical mouse model of autoimmune disorder." (PMID 32736564, 2020). "Also, SIRT6 was further found to be capable of delaying the onset of experimental autoimmune encephalomyelitis." (PMID 37096064, 2023).
injury (6 papers, 2017 to 2024). Damage inflicted on the body as the direct or indirect result of an external force, with or without disruption of structural continuity. "A previous study has shown that Sirt6 plays a critical protective role against alcohol-induced liver injury." (PMID 38649362, 2024). "The epigenetic modulator, sirtuin 6 (SIRT6), might protect the liver from oxidant stress during alcohol-induced liver injury." (PMID 35269779, 2022). "SIRT6, a member of the sirtuin family of NAD+-dependent deacetylases, has been shown to produce beneficial effects in brain injury and spinal cord injury." (PMID 34906231, 2021). "In addition to observations with SIRT6, it was demonstrated in a mouse model that low molecular weight fucoidan inhibited oxidative stress and mitochondrial dysfunction through the upregulation of the expression of SIRT3 after traumatic brain injury." (PMID 28635654, 2017).
lymphoma (6 papers, 2019 to 2024). A malignant (clonal) proliferation of B- lymphocytes or T- lymphocytes which involves the lymph nodes, bone marrow and/or extranodal sites. "Furthermore, elevated expression of SIRT6 was associated with shorter survival of cancer patients in the breast, stomach, lung, ovary, and lymphoma." (PMID 33198792, 2020). "In DLBCL, selective OSS_128167-mediated SIRT6 blockade inhibited PI3K/Akt/mTOR signaling and produced similar anti-lymphoma effects compared to SIRT6 knockdown in DLBCL cells." (PMID 39479446, 2024). "Selective OSS_128167-mediated Sirt6 blockage resulted in similar anti-lymphoma effects when compared to Sirt6 knocked-down DLBCL cells." (PMID 32711549, 2020). "OSS_128167, a novel targeted inhibitor of Sirt6, exerted excellent anti-lymphoma effects via inhibiting PI3K/Akt/mTOR signaling." (PMID 32711549, 2020). "In addition, OSS-128167 is a novel SIRT6 inhibitor and presents excellent anti-lymphoma effects by inhibiting PI3K/Akt/mTOR pathway." (PMID 35915188, 2022). "Targeting Sirt6 exerted anti-lymphoma activity and enhanced chemo-sensitivity." (PMID 32711549, 2020).
periodontitis (6 papers, 2022 to 2024). An acute or chronic inflammatory process that affects the tissues that surround and support the teeth. "This study showed that Sirt6 regulates inflammatory bone loss in ligature-induced periodontitis by suppressing osteoclast number and pro-inflammatory cytokines." (PMID 37445896, 2023). "This study offers the first elucidation of the role of Sirt6 in ligature-induced periodontitis, despite several limitations to explain the detailed mechanism of the protective effect of Sirt6 on alveolar loss." (PMID 37445896, 2023). "Our findings demonstrate that Sirt6 activation prevents bone loss against ligature-induced periodontitis." (PMID 37445896, 2023). "To verify the role of Sirt6 in alveolar bone loss induced by periodontitis, we used Sirt6-overexpressing Tg mice (Sirt6Tg)." (PMID 37445896, 2023). "Sirt6 had two roles in protecting against bone loss caused by ligature-induced periodontitis." (PMID 37445896, 2023). "Because Sirt6 plays a role in anti-inflammation and inhibition of osteoclast activity, we observed that reduced bone loss in Sirt6Tg mice against ligature-induced periodontitis results in blocking inflammation and osteoclasts." (PMID 37445896, 2023). "Therefore, we hypothesized that Sirt6 is essential in regulating inflammation and bone loss in periodontitis." (PMID 37445896, 2023). "Genetic and pharmacologic activation of SIRT6 ameliorates ligature-induced periodontitis by suppressing inflammation and decreasing the number and activity of osteoclasts." (PMID 38474862, 2024). "Second, Sirt6 had a role in regulating osteoclast number in a model of ligature-induced periodontitis." (PMID 37445896, 2023). "We also showed a protective effect of Sirt6 against ligature-induced periodontitis using Sirt6 overexpression in mice and a Sirt6 activator." (PMID 37445896, 2023). "The multi-mechanisms of Sirt6 in osteoblasts and osteoclasts that maintain bone homeostasis were thought to inhibit osteoclast numbers in ligature-induced periodontitis." (PMID 37445896, 2023). "First, Sirt6 had a role in regulating pro-inflammatory cytokines in a model of ligature-induced periodontitis." (PMID 37445896, 2023). "Taken together, genetic or pharmacologic activation of Sirt6 ameliorates ligature-induced periodontitis by suppressing inflammation and reducing the number and activity of osteoclasts." (PMID 37445896, 2023). "In the maxillary tissue of ligature-induced periodontitis, Sirt6 expression was downregulated, and inflammatory cell accumulation accompanied by inflammatory cytokines was observed." (PMID 37445896, 2023). "To verify the role of Sirt6 in periodontitis, we established a ligature-induced periodontitis mice model using nylon sutures." (PMID 37445896, 2023). "Next, we tested whether pharmacological Sirt6 activation was effective in ligature-induced periodontitis." (PMID 37445896, 2023). "Sirt6 expression suppresses inflammation and bone resorption; however, its role in periodontitis remains unclear." (PMID 37445896, 2023). "Additionally, the SPMs resolvin E1 and lipoxin A4 have been reported to inhibit NF-κB activation via sirtuins (Sirt1, Sirt6, and Sirt7) in pulpitis, supporting the therapeutic potential of a Sirt6 activator in periodontitis." (PMID 37445896, 2023). "MDL801, a Sirt6 activator, was used as a therapy for periodontitis through oral gavage." (PMID 37445896, 2023). "Moreover, we constructed m6SKO mice that underwent LIP-induced periodontitis to explore the in vitro and in vivo effect of SIRT6 on macrophage efferocytosis." (PMID 36593966, 2023). "To understand the role of Sirt6 in periodontitis, we compared periodontitis with ligature placement around the maxillary left second molar in 8-week-old control (C57BL/6J) male mice to Sirt6-overexpressing Tg (Sirt6Tg) mice, and we observed the resulting phenotypes using micro-CT." (PMID 37445896, 2023).
periodontitis (continued). "Considering the positive effects of host modulators for periodontitis in animal models and human clinical trials, the Sirt6 activator could be an adjunctive therapeutic strategy for periodontitis." (PMID 37445896, 2023). "Therefore, in this study, we aimed to examine the roles of KLF5 and SIRT6 in LPS-induced osteogenic differentiation and inflammatory response of PDLSCs so as to explore the pathogenesis of periodontitis." (PMID 35249460, 2022). "SIRT6 is also involved in the homeostasis modulation of periodontium during periodontitis." (PMID 36060706, 2022). "SIRT1 and SIRT6 might be of particular importance in relation to periodontitis." (PMID 38474862, 2024). "We hypothesized that Sirt6 has a protective role in periodontitis." (PMID 37445896, 2023). "Therefore, our results suggest that a Sirt6 activator could be used as a potential drug for periodontitis treatment." (PMID 37445896, 2023). "However, there have been few studies of the effect of SIRT6 on PDLSCswithi periodontitis." (PMID 35249460, 2022). "Thus, a Sirt6 activator may provide a new therapeutic approach for periodontitis." (PMID 37445896, 2023). "Sirtuin6 (SIRT6) and Krüppel-like factor 5 (KLF5) have been reported to regulate the inflammatory response and play an important role in the development of periodontitis." (PMID 35249460, 2022). "Interestingly, SIRT6 overexpression also promotes osteogenic differentiation and inhibits LPS-induced inflammatory response via suppressing NF-κB pathway in a periodontitis mode constructed by PDLSCs, which could be transcriptionally activated by Krüppel-like factor 5 (KLF5)." (PMID 36060706, 2022). "These pieces of evidence suggested that the Sirt6 activation may also alleviate symptoms in periodontitis, but there are no related studies yet." (PMID 37445896, 2023).
Werner syndrome (6 papers, 2012 to 2023). "In the nucleolus, SIRT6 associates with telomeres; SIRT6-deficient cells show abnormal end-to-end chromosomal fusion and premature senescence similar to that seen in Werner syndrome with premature ageing." (PMID 30216989, 2018). "It was shown to be required for the stable association of the Werner’s syndrome protein with telomeric chromatin and loss of function of SIRT6 leads to damage to telomeres and premature cellular senescence." (PMID 23240041, 2012). "In the Werner syndrome (premature aging disorder), deacetylation of SIRT6-dependent histone at telomeres produces a particular chromatin condition which is essential for DNA processing in the binding of ATP-dependent helicase of Werner syndrome (WRN)." (PMID 33920726, 2021). "At telomeric chromatin, SIRT6 deacetylated H3K9 and was required for the stable association of RECQL2/WRN, the factor that is mutated in Werner syndrome." (PMID 22792191, 2012). "Moreover, SIRT6-depleted cells exhibited abnormal telomere structures that resemble defects observed in Werner syndrome, a premature aging disorder." (PMID 22792191, 2012). "Indeed, SIRT6 localizes to telomeric chromatin where it facilitates the binding of Werner Syndrome (WS) protein, a DNA helicase crucial for genome stability." (PMID 36816109, 2023).
acute respiratory distress syndrome (5 papers, 2022 to 2026). Progressive and life-threatening pulmonary distress in the absence of an underlying pulmonary condition, usually following major trauma or surgery. "Sirtuin6 (SIRT6) has been demonstrated to be involved in a range of physiological processes and diseases, while its role in acute respiratory distress syndrome (ARDS) remains unclear." (PMID 37082736, 2023).
adenoma (5 papers, 2014 to 2023). A neoplasm arising from the epithelium. "To test this, we first analyzed the number of TICs present in the adenomas of control and SIRT6-deficient APCmin mice." (PMID 35314684, 2022). "Loss of SIRT6 in the intestinal epithelium of APCmin mice resulted in an increased number of adenoma-derived organoids, which were also larger in size." (PMID 35314684, 2022). "Downregulation/deletion of sirtuin 6 (SIRT6), a known repressor of tumor driver MYC is associated with adenoma formation and increased glycolysis during all stages of colorectal adenomas." (PMID 36618350, 2022). "Our pharmacological results agree well with recent reports stating that conditional intestinal ablation of SIRT6 increases the size and number and promotes the aggressiveness of adenomas in APCmin/+ CRC mice." (PMID 32483423, 2020). "Conditional deletion of Sirt6 in intestinal epithelium in mice prone to developing intestinal polyps (Apc+/min) results in a threefold increase in adenoma number." (PMID 25085992, 2014). "These adenomas are larger, with a greater propensity for invasive behavior, than those forming in SIRT6-proficient mice." (PMID 25085992, 2014).
age (5 papers, 2020 to 2025). A temporal measurement of the time period elapsed since an identifiable point in the life cycle of an organism. "Having determined the critical role of SIRT6 in regulating apoOBs clearance, we next sought to explore therapeutical strategies by enhancing SIRT6 expression in the context of age‐related bone loss." (PMID 37897313, 2023). "SirT6 promotes resistance to DNA damage and oxidative stress, the defects closely related to age‐associated diseases (Beauharmois, Bolivar, & Welch, 2013)." (PMID 31898815, 2020). "Importantly, cre‐dependent rAAV9 gene delivery and EC‐Exos drug delivery systems provided precise targeting strategies to enhance SIRT6 expression for preventing age‐related bone loss." (PMID 37897313, 2023). "Sirtuin 6 (SIRT6) reportedly suppresses age‐related diseases, such as metabolic diseases and cancer." (PMID 39224032, 2024). "Modulating SIRT6 activity by its pharmacological activation using specific drugs may, therefore, offer an attractive, non-invasive strategy to ameliorate age-dependent disc degeneration and to preserve disc health in the aging spine." (PMID 40335469, 2025). "In addition, PAI-1, whose expression was promoted by SIRT6 deficiency, was actively involved in bone metabolism, indicating that PAI-1 deficiency suppresses age-related bone loss." (PMID 37198221, 2023).
Anxiety (5 papers, 2016 to 2024). Intense feelings of nervousness, tension, or panic often arise in response to interpersonal stresses. "For example, 3TC has been shown to reduce anxiety and improve muscle function and bone density in the SIRT6 knockout mouse (a model of severe premature aging)." (PMID 36949552, 2023). "This was accompanied by rescue of the anxiety phenotype and a reduction in SIRT6." (PMID 35998298, 2023). "SIRT6 cKO mice showed comparable levels of anxiety in both elevated zero maze and open field tests." (PMID 30189861, 2018). "In addition, anxiety and locomotion were also normal in SIRT6 cKO mice." (PMID 30189861, 2018). "To exclude the possibility that SIRT6 overexpression in the CA1 impaired long-term memory is not due to the alteration of locomotor activity and/or anxiety-like behaviors; we investigated whether SIRT6 overexpression affects locomotor activity and anxiety-like behaviors." (PMID 26732053, 2016).
Arthritis (5 papers, 2017 to 2023). Inflammation of a joint. "In addition to arthritis, Sirt6 has significant anti-inflammatory properties in various inflammatory disease models, such as proteinosis, steatohepatitis and allergic airway inflammation." (PMID 35443857, 2022). "Consistent with SIRT6 inhibitory effects on the transactivation of NF-κB, an important regulator of osteoclast development, overexpression of SIRT6 suppresses RANKL-induced OC formation in vitro and bone destruction in mice with collagen-induced arthritis." (PMID 31590342, 2019).
bladder cancer (5 papers, 2015 to 2026). "Clinical analyses demonstrate that SIRT6 expression is frequently downregulated in bladder cancer and correlates with poor overall survival." (PMID 41463311, 2025). "How the deacetylase Sirtuin-6 (SIRT6) regulates glycolysis and lactate secretion in bladder cancer remains poorly defined." (PMID 39709438, 2024). "One mechanism of how E2F1 can enhance glycolysis is the suppression of the protein deacetylase enzyme SIRT6 in prostate- and bladder cancer cells." (PMID 27631473, 2016). "Functional studies with bladder cancer cell lines indicate that a major function of SIRT6 in bladder cancer is to down-regulate aerobic glycolysis." (PMID 25816777, 2015). "SIRT6 has emerged as a critical tumor suppressor in bladder cancer." (PMID 41463311, 2025). "We thus aimed to study the biological functions of SIRT6 in bladder cancer." (PMID 39709438, 2024). "Clinically, reduced SIRT6 expression coupled with elevated NCOA2 and mitochondrial/β-oxidation markers correlates with metastatic progression in bladder cancer." (PMID 41943834, 2026). "Consistent with the down-regulation of SIRT6 by E2F1, The expression of SRIT6 was significantly diminished when bladder cancers invaded deeper, i.e. progressed further on the tumor staging." (PMID 25816777, 2015).
colon adenocarcinoma (5 papers, 2018 to 2022). "SIRT6 deficiency could increase the incidence of invasive colonic adenocarcinoma in a mouse model expressing an adenomatosis polyposis coli mutation." (PMID 33335996, 2020). "SIRT6 has been identified in patients with colon adenocarcinoma and is related to the promotion of DNA repair in cells with DNA damage." (PMID 36497489, 2022). "The expression levels of SIRT6, glycolytic proteins and cellular metabolism were studied on human colon adenocarcinoma cells (Caco2)." (PMID 32905943, 2020). "Cyanidin, belonging to anthocyanins, increased SIRT6 protein expression in human colon adenocarcinoma (Caco2) cells." (PMID 32905943, 2020). "Moreover, the most potent activator, cyanidin, up-regulated SIRT6 protein expression on the human colon adenocarcinoma Caco-2 cells." (PMID 29515203, 2018). "Interestingly, the anthocyanidin cyanidin (3c), which showed 55-fold activation of SIRT6 activity and EC50 = 460 μM, increased also SIRT6 expression levels in a dose-dependent fashion and exhibited important effects in colon adenocarcinoma Caco-2 cells." (PMID 33800266, 2021).
ischemia (5 papers, 2016 to 2025). A hypoperfusion of the BLOOD through an organ or tissue caused by a PATHOLOGIC CONSTRICTION or obstruction of its BLOOD VESSELS, or an absence of BLOOD CIRCULATION. "Overall, our study signifies a critical turning point in understanding the regulation of AIM2-pyroptosis and mitophagy under ischemia–reperfusion conditions, supporting the exploration of Sirt6-enriched adipose stem cell-derived exosomes as a practical clinical treatment." (PMID 38172884, 2024). "Therefore, regulation of autophagy by controlling SIRT6 levels might be a promising therapeutic target for ischemia and other brain diseases." (PMID 26983852, 2016). "In intestinal ischemia–reperfusion (II/R) injury, miR-351-5p was shown to target MAPK13 and sirtuin-6, activate the Bcl2-1/NF-κB signaling pathway and cleave caspase-3, which promotes cell death." (PMID 37686375, 2023).
liver disease (5 papers, 2018 to 2021). "We are optimistic that these findings will promote the development of allosteric activators of Sirt6 for treatment of cholestasis and associated liver disease." (PMID 32701506, 2020). "Importantly, our previous study has found that SIRT6 played a positive role in the development of HCC by enhancing tumor growth and inhibiting apoptosis, suggesting the pivotal role of SIRT6 in liver disease." (PMID 31708789, 2019). "In addition to glucose metabolism, cancer, and aging related processes, SIRT6 has also been shown to be a negative regulator of triglyceride synthesis and affect liver disease." (PMID 29966233, 2018).